TTC9-DT (TTC9 divergent transcript)
Gene: Long non-coding RNA gene on chromosome 14 (70,608,798 to 70,641,298, reverse strand). Ensembl gene ENSG00000245466.
Gene Ontology:
Biological process: SRP-dependent cotranslational protein targeting to membrane, signal sequence recognition
Cellular component: signal recognition particle, endoplasmic reticulum targeting